CD274 (CD274 molecule)
Diseases named in the same sentence as CD274 in open-access papers (continued):
Sharing a sentence is not in itself a finding about the gene and the disease.
invasive breast carcinoma (39 papers, 2014 to 2025). A carcinoma that infiltrates the breast parenchyma. "We initially determined CD274 (encodes PD-L1) mRNA expression within the TCGA dataset in invasive breast carcinoma (BRCA)." (PMID 35717238, 2022). "More recently, Breg expression of PD-L1 (also known as CD274) has been recognized as an important mediator of their immunosuppressive function, both in mouse models and invasive breast cancer patients." (PMID 30355585, 2018). "An increase in PDCD1 and CD274 expression was correlated with better overall survival (OS) and disease-specific survival (DSS) in TNBC and breast-invasive carcinoma." (PMID 40278313, 2025).
periodontitis (35 papers, 2016 to 2025). An acute or chronic inflammatory process that affects the tissues that surround and support the teeth. "Only CD274 (programed death-ligand 1 with a major role in suppressing the immune system through a signal that inhibits TCR-mediated activation of IL-2 production and T cell proliferation) and ID3 (DNA-binding protein inhibitor ID-3 is a transcription inhibitor) were decreased with periodontitis." (PMID 27486459, 2016).
uveal melanoma (35 papers, 2019 to 2025). A melanoma derived from melanocytes of the uveal tract. "In GSE155452 uveal melanoma cell line (mel202), after romidepsin intervention, the expression of CD274 was significantly increased, and the expression of TNFRSF9 and TNFRSF14 was significantly different." (PMID 34635662, 2021). "Similarly, in uveal melanoma (UVM) and liver hepatocellular carcinoma (LIHC), CRABP2 expression is significantly correlated with seven of these immune checkpoint genes (LAG3, CTLA4, PDCD1LG2, HAVCR2, PDCD1, CD274, and TIGIT)." (PMID 39991584, 2025).
asthma (34 papers, 2015 to 2025). "The marked elevation of IL-18 is particularly notable when considering recent work highlighting the role of IL-18 in promoting a pathogenic CD101 + CD274 + eosinophil phenotype associated with the pathogenesis of both eosinophilic esophagitis and asthma." (PMID 41013452, 2025). "Cd274 and Pdcd1 were reported to be important for the activation of T lymphocytes in asthma and PD-1 expression increased in T-CD4+ lymphocytes of asthmatic patients." (PMID 34440118, 2021). "Among them, Cd274 (PD‐L1) and Pdcd1 (PD‐1) are shown to be important for the activation of T lymphocytes in asthma." (PMID 33942458, 2021). "Activation markers, such as integrin Mac-1 (CD11b/CD18), L-selectin (CD62L), CBRM1/5, ICAM-1 (CD54), PD-L1 (CD274), PSGL-1 (CD162), FcγRII (CD32), CD16, CD44, and CD69, were shown to be upregulated on circulating or sputum granulocytes from asthma patients." (PMID 32731346, 2020).
medulloblastoma (33 papers, 2013 to 2026). A malignant, invasive embryonal neoplasm arising from the cerebellum. "In addition, the method identified the PDCD1LG2/CD274 region, 17p13.3, a region that has been implicated as a tumor-suppressor region in medulloblastoma, where it is deleted in 40% of cases and ARID1B, a member of the SWI/SNF chromatin remodeler complex implicated in differentiation and development." (PMID 23531283, 2013). "IHC showed no PD‐L1 protein expression in the medulloblastoma, in the primary dpHGG, and in the PDX of dpHGG, corroborating the low CD274 mRNA levels." (PMID 40880425, 2025). "We found that canonical immune checkpoints, such as CTLA4, PDCD1 (PD1), and CD274 (PD‐L1), are absent or exhibit a very low mRNA expression in the medulloblastoma, dpHGG, and PDX." (PMID 40880425, 2025). "We could corroborate in this large dataset of 763 medulloblastomas the low levels of PDCD1 (PD-1), CD274 (PD-L1), and CTLA4." (PMID 36825029, 2023).
Stroke (33 papers, 2013 to 2025). Sudden impairment of blood flow to a part of the brain due to occlusion or rupture of an artery to the brain. "Transcriptional analysis confirmed a reduction in expression of co-stimulatory genes in the spleen known to be expressed by macrophages 1–5 days after experimental stroke including Cd40, Cd80, Cd86, Icam1, Tnfsf9, which encodes 4-1BBL, and Cd274." (PMID 29872438, 2018). "T cell subpopulations (CD4+, CD8+, DNT) and their activation (CD25, CD57, CTLA-4 (CD152) and PD-L1 (CD274)) were analysed in peripheral blood from stroke patients and controls by flow cytometry." (PMID 41373643, 2025). "Previous studies indicate that CD274, also known as PD-L1, exacerbates inflammation in stroke, and treatments with anti-PD-L1 antibodies control CNS inflammation." (PMID 40536592, 2025).
vitiligo (33 papers, 2017 to 2025). Generalized well circumscribed patches of leukoderma that are generally distributed over symmetric body locations and is due to autoimmune destruction of melanocytes. "To date, no single-nucleotide polymorphisms in the PD-1 (PDCD1) or PD-L1 (CD274) gene has been reported in human vitiligo." (PMID 33240267, 2020).
gynecological cancers (32 papers, 2018 to 2026). "Significant upregulation of CD274 expression was observed in tumors with high SELENOI expression, including gynecological cancers." (PMID 39669976, 2024). "In gynecologic cancers, EC showed the highest overexpression of programmed cell death 1 (PD-1, CD279) and programmed cell death ligand 1 (PD-L1, CD274): 40–80% in endometrioid carcinoma, Serous carcinomas accounted for 10–68% of tumors, and clear cell tumors accounted for 23–69%, respectively." (PMID 37853361, 2023). "Among gynecological cancers, EC displays the highest overexpression of programmed cell death 1 (PD-1, CD279) and programmed cell death ligand-1 (PD-L1, CD274): 40–80% for endometrioid cancers, 10–68% for serous tumors, 23–69% for clear cells tumors, respectively." (PMID 34199461, 2021).
prostate tumor (32 papers, 2016 to 2025). "We identified the upregulation of immunomodulatory molecules, such as IDO1, TIM3, and CD274(PD-L1), in both prostate tumors expressing higher levels of MHC-I and -II genes." (PMID 38704603, 2024).
immune deficiency (31 papers, 2017 to 2025). "Costimulatory proteins Cd274 (PD-L1), Ctla4 and Cd86 linked to the immune deficiencies observed in sepsis were upregulated across tissues (12/13 tissues for Cd274, 6/13 tissues for Cd86 and 3/13 tissues for Ctla4)." (PMID 38191855, 2024). "The immune escape and immune deficiency scores, along with the CD274 score, suggested that patients in the high-ERScore group were more likely to have a poor response to immunotherapy." (PMID 37313465, 2023). "On the other hand, RNA-seq data revealed that a variety of immune deficiency markers, such as CD274 (PD-L1), CTLA4, NRP1, and LAGLS9, were increasingly expressed in the high-risk group, which was in line with our previous findings as regards immune suppression of cluster 1 determined by ROGs." (PMID 37252189, 2023). "Furthermore, the immune escape and immune deficiency scores, as well as the CD274 score, suggested that patients in the high-scoring group were more likely to be less responsive to immunotherapy." (PMID 37313465, 2023). "Similarly, immune deficiency markers, such as CD274 (PD-L1), CTLA4, NRP1, and LAGLS9, were increasingly expressed in the high GRORS tumors." (PMID 37252189, 2023). "Over the last decade, monoclonal antibodies targeting programmed cell death protein 1 (PD-1, also known as PDCD1 and CD279) or programmed cell death ligand 1 (PD-L1, also known as CD274 and B7-H1) to restore tumor-induced immune deficiency have emerged as a promising treatment." (PMID 35139879, 2022). "Therefore, the aim of this publication was to evaluate three immunological checkpoints of their ligands: PD-1 (CD279)/PD-L1 (CD274), CTLA-4 (CD152)/CD86, and CD200R/CD200 in the course of immunodeficiencies, on the example of CLL and CVID." (PMID 37958359, 2023).
malignant pleural mesothelioma (31 papers, 2015 to 2026). A malignant neoplasm that arises from mesothelial cells in the pleura and shows a diffuse growth pattern. "We investigated whether inhibition of YAP down‐regulates PD‐L1 (CD274) in human malignant pleural mesothelioma (MPM)." (PMID 29575535, 2018).
skin cancer (30 papers, 2018 to 2026). "Moreover, blocking antibodies against some of those receptors, such as programmed cell death (PD)-1 (CD279) and programmed cell death ligand (PD-L)-1 (CD274, B7-H1), expressed by T cells and antigen presenting cells (APCs), respectively, could restore T cell function in skin cancer." (PMID 33193363, 2020).
gallbladder cancer (29 papers, 2018 to 2025). "In the epithelium of gallbladder cancer, the expression of epithelial CD274 is higher in the ASPH high-expression group (p value = 7.5e-10)." (PMID 40110547, 2025).
testicular germ cell tumor (28 papers, 2017 to 2025). A germ cell tumor arising from the testis. "The results showed that in BLCA (P < 0.001), BRCA (P < 0.001), COAD (P < 0.05), and THCA (P < 0.001), PCSK9 was positively correlated with PDCD1, CD274, and CTLA4 but negatively correlated in HNSC (P < 0.05) and testicular germ cell tumor (TGCT) (P < 0.01)." (PMID 38600469, 2024). "Additionally, UPF3B expression was positively correlated with most immunoinhibitors, including TGFBR1, IL10RB, CD160, CD274, TIGIT and PDCD1 in UVM, OV, KIHC, and LIHC, but negatively associated with the expression of majority genes in STAD and Testicular Germ Cell Tumors (TGCT)." (PMID 36194583, 2022).
squamous non-small cell lung cancer (27 papers, 2017 to 2026). "We sought to characterize response to immune checkpoint inhibitor (ICI) in non-squamous non-small cell lung cancer (NSCLC) across various CD274 copy number gain and loss thresholds and identify an optimal cutoff." (PMID 35598202, 2022).
colorectal adenocarcinoma (26 papers, 2017 to 2025). The most common type of colorectal carcinoma. "During the follow‐up period of the two USA‐wide prospective cohort studies, we identified 4465 incident colorectal adenocarcinoma cases, including 812 cases with available data on tumor CD274 (PD‐L1) expression and F. nucleatum in tumor tissue." (PMID 37538192, 2023). "We confirmed a significant correlation in mRNA levels between AGR2 and CD274 in the GDAC Firehose dataset (previously known as TCGA provisional) as well as in Colorectal Adenocarcinoma TCGA PanCancer Atlas consisting of 526 samples/patients." (PMID 39300184, 2024). "In our study, AP3M2 was found to be positively related to PD-L1(CD274), hypoxic response, NF-kB pathway, and NK cell infiltration in colorectal adenocarcinoma." (PMID 38177168, 2024).
Cirrhosis (24 papers, 2017 to 2025). A chronic disorder of the liver in which liver tissue becomes scarred and is partially replaced by regenerative nodules and fibrotic tissue resulting in loss of liver function. "Unexpectedly, there was no significantly differences for PD-L1 (CD274) in cirrhosis tissues compared with normal liver tissue." (PMID 36229881, 2022).
experimental autoimmune encephalomyelitis (24 papers, 2009 to 2025). An autoimmune demyelinating disease of the central nervous system that is produced experimentally in animals by the injection of homogenized brain or spinal cord in Freund's adjuvant. "Here we studied the role of the co-inhibitory molecule B7-H1 (PD-L1, CD274) on semi-mature DC that were generated from bone marrow (BM) cells of B7-H1−/− mice and applied to the model of Experimental Autoimmune Encephalomyelitis (EAE)." (PMID 20520738, 2010).
myositis (24 papers, 2017 to 2025). "CNVs on PRDM1 and CD274 were significantly linked to encephalitis (p = 0.014 and p = 0.032) and myositis (p = 0.014 and p = 0.032)." (PMID 35053465, 2022). "The occurrence of myositis as well as encephalitis was associated with CNVs on CD274 and PRDM1 in our study, possibly explaining the combined occurrence of these IRAE in clinical practice." (PMID 35053465, 2022). "Myositis and encephalitis, both, were associated with alterations of PRDM1 and CD274, which might explain their joined appearance in clinical practice." (PMID 35053465, 2022). "Finally, CNVs on PRDM1 and CD274 were significantly linked to encephalitis, and CNVs on PRDM1, CD274, TSHR and FAN1 were significantly linked to myositis." (PMID 35053465, 2022).
myocardial infarction (22 papers, 2015 to 2026). Gross necrosis of the myocardium, as a result of interruption of the blood supply to the area, as in coronary thrombosis. "Mechanically, HLA complex P5 (HCP5) and myocardial infarction associated transcript (MIAT), upregulated the expression of PD-L1/CD274 by sponging miR-150-5p, which is regulated by the transcriptional axis of lip-polysaccharides (LPS) -CCCTC binding factor (CTCF)." (PMID 36810034, 2023).
parasitemia (22 papers, 2012 to 2026). "Several consecutive studies have confirmed that the PDCD1/PD-L pathway is exploited by a panel of viral and parasitic infections as target for immune evasion, mostly by increasing CD274 on APCs." (PMID 25940792, 2015).
cervical adenocarcinoma (20 papers, 2019 to 2026). An adenocarcinoma arising from the cervical epithelium. "Cervical adenocarcinomas exhibit significantly lower CD274 (PD-L1) expression and a poorer response to immune checkpoint inhibitors (ICIs)." (PMID 41742943, 2026).
Hyperglycemia (20 papers, 2016 to 2025). An increased concentration of glucose in the blood. "The protein expression of CD36, CD69, and CD274 was increased with hyperglycemia compared to control cells as evidenced by increased fluorescence." (PMID 41465460, 2025). "The mechanistic effects of hyperglycemia on CD274 expression have been investigated in other diseases, mainly oncoloy, but not in healing wounds." (PMID 41465460, 2025). "Hyperglycemia also modulated the expression of CD274 and TLR-7." (PMID 41465460, 2025). "Increased expression in fibroblasts with hyperglycemia is supported by the fact that fibroblasts may express CD274 in certain conditions." (PMID 41465460, 2025). "Limitations of the study and future perspective: The study highlights the effects of hyperglycemia on the expression of CD36, CD69, CD274, and TLR-7 in rat tissues and rat fibroblasts." (PMID 41465460, 2025). "This study aims to investigate the effects of hyperglycemia on the expression of various factors, including surface receptors CD36, Toll-like receptor (TLR)-7, programmed death-ligand 1 (PD-L1, also known as CD274), and CD69, in tissues from diabetic rats compared to control rats." (PMID 41465460, 2025). "However, the effects of hyperglycemia on the expression of mediators of inflammation and angiogenesis (CD36), immune regulation (TLR-7 and CD69), and inflammation/tissue repair (CD274) regarding wound healing are unknown." (PMID 41465460, 2025). "Beyond acute metabolic stress, the emerging concept of metabolic memory suggests that prior hyperglycemia may imprint checkpoint gene loci, such as PDCD1 and CD274, with persistent epigenetic marks, although direct demonstration in vascular tissues is required for validation." (PMID 41463504, 2025). "Hyperglycemia significantly increases the expression of CD36, CD69, and CD274 and increases TLR-7 expression but not significantly in diabetic tissues compared to control tissues." (PMID 41465460, 2025).
Lynch syndrome (20 papers, 2017 to 2025). An autosomal dominant hereditary neoplastic syndrome characterized by the development of colorectal carcinoma and a high risk of developing endometrial carcinoma, gastric carcinoma, ovarian carcinoma, renal pelvis carcinoma, and small intestinal carcinoma. "A retrospective Japanese study of CRC suggests that sporadic MSI cancers compared to Lynch-syndrome-associated cancers more frequently develop as poorly differentiated, solid-type tumors with a medullary morphology, and many express CD274 (25.0 vs. 3.6%, p = 0.034)." (PMID 36013315, 2022). "The predictive role of CD274 in dMMR CRC and its possible correlation with Lynch syndrome remain interesting suggestions that deserve to be explored in future studies." (PMID 36013315, 2022).
follicular lymphoma (19 papers, 2017 to 2025). Follicular lymphoma is a form of non-Hodgkin lymphoma characterized by a proliferation of B cells whose nodular structure of follicular architecture is preserved. "If this conventional approach fails, somatic mutation analysis should assist their differential diagnosis, in light of the remarkable differences in the mutation profile between thyroid MALT lymphoma and follicular lymphoma, particulalry the highly frequent CD274 and TET2 mutations in the former." (PMID 34021249, 2021).
Granuloma (19 papers, 2010 to 2025). A compact, organized collection of mature mononuclear phagocytes, which may be but is not necessarily accompanied by accessory features such as necrosis. "For instance, whole transcriptome co-mapping at cellular resolution with spatial CITE-seq could validate the spatial expression patterns of CD274, IRF1, and HPSE within granulomas or inflammatory niches, clarifying their roles in local immune modulation." (PMID 40607433, 2025).
leishmaniasis (18 papers, 2014 to 2025). Infectious disease that is transmitted through the bite of hematophagous female phlebotomine sand flies. "In the context of leishmaniasis, the biological role and expression pattern of IL-24 is poorly studied, with one preprint report showing elevated levels of IL-24 in CD274+ and IDO1+ myeloid cells in human CL skin lesions." (PMID 39364404, 2024).
acute kidney injury (16 papers, 2016 to 2026). Sudden and sustained deterioration of the kidney function characterized by decreased glomerular filtration rate, increased serum creatinine or oliguria. "Further significantly upregulated transcripts related to inflammatory processes included ADAM19, PD-L1 (CD274), non-canonical NF-kB genes NFKB2 and RELB, furthermore IFITM1, JAML -linked with acute kidney injury - IRX3-linked with metabolic inflammation - and PRDM1-observed in gouty arthritis." (PMID 40281125, 2025).
heart failure (16 papers, 2019 to 2026). Inability of the heart to pump blood at an adequate rate to meet tissue metabolic requirements. "Our analysis revealed that CD274 (PD-L1) was enriched in adult heart failure tissues compared with non-HF tissues." (PMID 38012001, 2024).
laryngeal squamous cell carcinoma (16 papers, 2016 to 2024). A squamous cell carcinoma that arises from the larynx. "Sun and colleagues attested that CD274 (an alias of PD‐L1) was overexpressed in laryngeal squamous cell carcinoma (LSCC) tissues and the elevated level of CD274 was relative to a lower survival rate among LSCC patients." (PMID 35347894, 2022).
lung diseases (14 papers, 2015 to 2026). "Notably, its expression correlated with pulmonary disease burden and preceded progression to active TB, in line with previous work demonstrating upregulation of CD274 in patients with active TB66." (PMID 35058616, 2022). "A recent study demonstrated that nine genes (CD274, CEACAM1, CR1, FCGR1A/B, IFITM1, IRAK3, LILRA6, MAPK14, and PDCD1LG2) showed 100% sensitivity and specificity that distinguished patients with active TB from those with other lung diseases (OPD)." (PMID 38674369, 2024).
myeloid leukemia (14 papers, 2019 to 2025). A clonal proliferation of myeloid cells and their precursors in the bone marrow, peripheral blood, and spleen. "In the K562 human immortalized myelogenous leukemia cell line, FOXM1 enrichment was noted on the promoter region with a peak signal of ≈167 bp upstream of the CD274 transcription start site." (PMID 35975458, 2022).
myeloproliferative neoplasm (14 papers, 2019 to 2024). A clonal hematopoietic stem cell disorder, characterized by proliferation in the bone marrow of one or more of the myeloid (i.e., granulocytic, erythroid, megakaryocytic, and mast cell) lineages. "Furthermore, one of the targets downregulated by miR-142-5p is CD274, which encodes PD-L1 that is elevated in many cancer types, including myeloproliferative neoplasms (MPNs)." (PMID 35764886, 2022).